TNF (tumor necrosis factor)
Diseases named in the same sentence as TNF in open-access papers (continued):
Sharing a sentence is not in itself a finding about the gene and the disease.
Insulin resistance (continued). "In turn, TNF-α activates the JNK and IKK kinases, which phosphorylate the insulin receptor substrate (IRS)-1 and then impair the insulin-induced uptake of glucose, resulting in insulin resistance." (PMID 38257152, 2024). "Additionally, TNFα and IL-6 enhance PAI-1 and TF in adipose tissue, further exacerbating the procoagulant state, insulin resistance, and MCP-1 production from adipocytes and endothelial cells in adipose tissue." (PMID 39858414, 2024). "Additionally, 4 weeks of HIIT can decrease the F/B ratio in insulin-resistant patients, reduce serum levels of TNF-α, C-reactive protein (CRP), and lipopolysaccharide-binding protein (LBP), improving systemic insulin resistance." (PMID 39834360, 2024). "TNF-α triggers production of pro-inflammatory cytokines and increases IRS-1 serine phosphorylation by regulating the MAPK and NF-κB pathways, thereby inducing inflammation and insulin resistance." (PMID 38257186, 2024). "Additionally, there was a positive correlation found between inflammatory markers (hs-CRP, MCP-1, TNF-alpha, and PAI-1 levels), lipid profiles (LDL-c, TG, and TC levels), and insulin resistance (fasting glucose level, fasting insulin level, and HOMA-IR)." (PMID 38463431, 2024). "TNF-α is thought to reduce insulin signaling by decreasing the phosphorylation of the insulin receptor substrate-1 (IRS-1) Tyr632 and Akt Ser473, which are downstream effectors of the insulin receptor, thereby resulting in insulin resistance." (PMID 39200235, 2024). "The biological mechanisms underlying MASLD leading to HCC involve the release of inflammatory cytokines (such as TNF-α, IL6) and reduced adiponectin levels that promote insulin resistance, which in turn inhibits fatty acid oxidation, leading to DNA damage and mutations." (PMID 38987736, 2024). "If these alterative inflammatory mediators are important in human insulin resistance, then it would not be surprising that drugs targeting TNF-α and other “classical” cytokines would be inefficacious in reversing insulin resistance." (PMID 39225103, 2024). "Furthermore, the GPE exhibited an additional effect by mitigating the inflammation mediated by tumor necrosis factor-α (TNF-α) and alleviating insulin resistance (IR) in primary cultures of human adipocytes." (PMID 38987806, 2024). "The proinflammatory cytokine, tumor necrosis factor α (TNFα), suppresses the phosphorylation of AMPK and increases the expression of protein phosphatase 2C (PP2C) in the skeletal muscles thereby inducing insulin resistance." (PMID 36875093, 2023). "The hypoglycemic property might also be explained by its impact on the PI3K/Akt, MAPK, TNF, TLR, and estrogen signaling, cancer, insulin resistance, and JAK-STAT pathways." (PMID 37719108, 2023). "TNFα induces mitochondrial dysfunction, oxidative stress, and insulin resistance, which activate the adipose NLRP3 inflammasome without altering IL-1β." (PMID 37876013, 2023). "The hypoglycemic mode of action of Cyanotis arachnoidea may be mediated by tumor necrosis factor (TNF) signaling, cancer, insulin resistance, and JAK-STAT pathways." (PMID 37719108, 2023). "Thus, the increased secretion of TNF, IL1B, and CCL2 in the hepatic macrophages of old mice potentially aggravates insulin resistance, liver steatosis, and the progression of chronic liver diseases." (PMID 37602516, 2023). "The observed results in this study regarding the serum TNF-α and IL-6 levels could be explained by the metabolic disturbances induced by DEXA that led to an insulin resistance state; this was observed in similar animal studies." (PMID 37894792, 2023). "Effects of TNF-α on adipose tissue are primarily mediated through TNF-α receptor 1 (TNFR1) and include an increase in insulin resistance, induction of apoptosis and activation of pro-inflammatory signaling pathways, which in turn favors metabolic dysregulation." (PMID 36830779, 2023).
Insulin resistance (continued). "Finally, it has been shown that in vitro, TNF-α stimulates the production of diacylglycerol (DAG) and ceramide, which are involved in the pathogenesis of insulin resistance in skeletal muscle." (PMID 36860845, 2023). "From KEGG enrichment analysis, the AGE-RAGE, PI3K-Akt, IL-17, MAPK, TNF, EGFR, HIF-1, Apoptosis, Toll-like receptor, Insulin resistance, VEGF, Rap1, NF-kappa B, JAK-STAT, PPAR and Wnt pathway were displayed as the critical signaling participated in the role of QDDHG on DKD." (PMID 37954274, 2023). "Adipocytes can secrete a variety of hormones and cytokines, namely tumor necrosis factor (TNF)-α, interleukin (IL)-6, and resistin, which are able to induce a chronic inflammatory state and insulin resistance, with consequences primarily on adipose, muscular, and hepatic tissues." (PMID 37107279, 2023). "Thus, it is not surprising that key proinflammatory cytokines, including TNF-a, IL-6, CCL2, and CCL5, which are present at high serum concentrations in patients with insulin resistance, are mediators of HSC activation." (PMID 37735474, 2023). "TNFα negatively affects insulin signaling by attenuating the insulin-stimulated tyrosine phosphorylation of the insulin receptor and insulin receptor substrate 1 (IRS1) in the WAT and muscles, leading to insulin resistance." (PMID 37755259, 2023). "Then, it could be explained through resistin’s effect in inflammation-induced insulin resistance, probably due to its activity over inflammatory cytokines, such as IL6, IL-12, TNF-α, and (NF-κB)." (PMID 37238961, 2023). "For instance, it is known that TNF-α is related to GDM by inducing adipocyte lipolysis, which can lead to a decreased insulin sensitivity by peripheral tissues, thus being considered as a biomarker for insulin resistance in pregnancy." (PMID 37367903, 2023). "Scientists then found that local inflammation was significantly aggravated by measuring inflammatory markers such as TNF-α, IL-4, and TOLL4, indicating that the development of eATP-induced insulin resistance may be due to several inflammatory responses." (PMID 36918975, 2023). "Circadian rhythm dysfunction promotes the secretion of inflammatory cytokines (TNFα, IL-1β, and IL-6), which induces insulin resistance and makes a negative effect on the production of GnRH and LH." (PMID 37229470, 2023). "However, low and high dosage administration of vitamin A decrease TNF-α and IL6 on obese adults; therefore, reducing insulin resistance, and improving energy expenditure." (PMID 36776154, 2023). "TNF-α promotes the activity of a series of proteins such as IKK that act directly on the substrate (IRS) of the insulin receptor, leading to the development of insulin resistance in muscle cells." (PMID 36918975, 2023). "Indeed, several studies have reported increased levels of TNF-α, IL1-β, and IL-6 in adipose tissue that can lead to insulin resistance." (PMID 37892881, 2023). "Moreover, TNF-α positively regulates PAI-1 gene expression which, in turn, induces insulin resistance, and metabolic abnormalities in liver, muscle, and fat during proinflammatory processes." (PMID 37514235, 2023). "Moreover, there is accumulating evidence on the fact that inflammatory cytokines possibly derived from adipose tissue, such as tumor necrosis factor-α (TNF-α), contribute to the development of insulin resistance." (PMID 37513560, 2023). "TNF-α is a key mediator in the process of MASLD development by not only promoting inflammatory response, but also mediating insulin resistance, and inducing fibrosis-associated proteins." (PMID 38082368, 2023). "Probably it is due to CBD and THC’s ability to attenuate TNF-α elevation observed in patients with metabolic disorders, and as we know, TNF-α seems to be a prominent pro-inflammatory cytokine and factor promoting insulin resistance." (PMID 37510734, 2023).
Insulin resistance (continued). "We focused on the protein levels of proinflammatory cytokines such as NF-κB, TNF-α, INF-γ, and IL-6 in both control and experimental rats to ascertain whether kiwi extract can lessen inflammation and insulin resistance brought on by HFD and STZ." (PMID 37762060, 2023). "The highest downregulated protein was chitinase-3-like protein 1, a glycoprotein consisting of 383 amino acids with a molecular mass of 40 kDa, which counteracts TNFα-mediated inflammation and insulin resistance in SkM cells." (PMID 36671013, 2023). "Despite the inter-relationship between IL-6, TNF-α and CRP, this study neither found similar associations between IL-6 and TNF-α with insulin resistance nor with other metabolic outcomes." (PMID 37891561, 2023). "It was observed that mice lacking TNF-α or its receptor are resistant to the development of insulin resistance." (PMID 37014444, 2023). "Additionally lipolytic actions of tumor necrosis factor α (TNF-α), which promotes insulin resistance, can be attenuated by hesperetin in 3T3-L1 cells." (PMID 37697354, 2023). "Despite the positive correlations found between plasma TNF levels and peripheral insulin resistance, the neutralization and antagonization of TNF have not been shown to improve insulin resistance in humans." (PMID 36766750, 2023). "The implications of TNF-α in numerous biological processes are manifold and significant: TNF-α is involved in leukocyte trafficking and immune clearance, the promotion of dyslipidemia and insulin resistance, the formation of granulomas, and immune homeostasis." (PMID 37180165, 2023). "These proinflammatory cytokines are critical to the onset of insulin resistance; mice lacking TNF-α have lower circulating free fatty-acids and are protected from insulin resistance." (PMID 36726470, 2022). "Tumor necrosis factor alpha (TNF-α), which is a pro-inflammatory cytokine, can destroy the tyrosine phosphorylation activation of IR and IR substrate (IRS) in the insulin signaling cascade, thereby leading to insulin resistance." (PMID 35846289, 2022). "There was a positive correlation between miR-17-5p, and miR-20a-5p and insulin resistance, but not with tumor necrosis factor- α (TNF-α) or BMI." (PMID 36704034, 2022). "An increased production of TNF, IL-6, MCP-1, and other products of macrophages and other cells that occupy adipose tissue may consequently also play a role in the development of insulin resistance." (PMID 35959181, 2022). "In addition, stroke is characterized by the development of inflammation and some proinflammatory cytokines, such as tumor necrosis factor (TNF), seem able to activate the HPa axis and induce insulin resistance." (PMID 35216512, 2022). "Each of these models exhibits insulin resistance and impaired glucose metabolism, which was demonstrated by a glucose tolerance test (GTT) and insulin tolerance test (ITT), and systemic inflammation characterized by elevated plasma IL-6 and TNF-α levels." (PMID 35327570, 2022). "In this context, the expression of proinflammatory cytokines in adipose tissues is significantly enhanced, including Interleukin (IL)-6 and tumor necrosis factor (TNF)-α, which can result in insulin resistance mainly via the inactivation of insulin receptor by phosphorylating the serine on it." (PMID 36339448, 2022). "Moreover, aerobic exercise attenuated insulin resistance by regulating the IRS-1/PI3K/AKT and the TNF-α/NF-κB signaling pathways." (PMID 36145106, 2022). "The secondary outcome was dietary intake, anthropometric indices, serum insulin and Homeostatic Model Assessment of Insulin Resistance (HOMA-IR), total antioxidant capacity (TAC), tumor necrosis factor (TNF), high-sensitivity C-reactive protein (hs-CRP), malondialdehyde (MDA), and lipid profile." (PMID 35870947, 2022).
Insulin resistance (continued). "Evaluating pre and post values, Hesperidin was able to reduce the serum levels of glucose (p < 0.001), insulin (p < 0.001), the homeostasis model assessment of insulin resistance (HOMA-IR) (−0.70, p < 0.001) TG (p = 0.002), TC (p < 0.001), LDL-c (p = 0.010), TNF-α (p < 0.001) and hs-CRP (p = 0.008)." (PMID 35955475, 2022). "Different models of insulin resistance induction have been applied to SGBS cells including chronic high insulin and/or glucose or pro-inflammatory factors such as interferon gamma, TNFα, or IL-29." (PMID 35986215, 2022). "In addition, the up-regulated genes were enriched toll-like receptor signaling pathway, insulin resistance, FOXO signaling pathway, TNF signaling pathway, etc., by KEGG pathway analysis." (PMID 35906673, 2022). "However, for the validated genes, IRS-1 was overexpressed and TNFα was downregulated post-RYGB in both low and high insulin resistance." (PMID 36432612, 2022). "Additional in vivo experiments revealed that asprosin augmented glucose intolerance, insulin resistance, endoplasmic reticulum (ER) stress, as well as circulation of pro-inflammatory cytokines (monocyte chemoattractant protein-1, MCP-1; IL-6; and TNFα) in mice." (PMID 36613673, 2022). "Macrophages participate in inflammatory pathways including JNK, IKK/NF-κB, and JAK/STAT through secreting inflammatory factors, such as TNF-α, IL-6, IL-1β, and LTB4, thereby inducing chronic inflammation of adipose tissue, liver, and muscle, further leading to insulin resistance." (PMID 36230963, 2022). "KEGG enrichment results demonstrated that YLZD might against NAFLD by regulating the TNF, PI3K/AKT, HIF-1, insulin resistance (IR), and other signaling pathways." (PMID 35721171, 2022). "In vitro analysis confirmed that DPHB could improve insulin resistance and glycolipid metabolism disorders through PI3K/AKT and TNF-α signaling pathways." (PMID 36120365, 2022). "Notably, pathways involved in inflammatory processes, such as TNF-α and TGF-β, were suppressed in ductal clusters from grafts transplanted in mice with insulin resistance, as well as in T2D β cells in comparison with their respective controls (CTRL)." (PMID 35819843, 2022). "TNF-α is overexpressed in the adipose tissues of obese humans and animals alike, whereas obese mice without TNF-α or its receptor are reportedly immune to insulin resistance." (PMID 35743146, 2022). "Moreover, TNF-α, IL-6, IL-1β, IFN-γ are also related to insulin resistance in the pediatric population." (PMID 36146688, 2022). "In NASH progression, TNF-α induces the activation of JNK, leading to the Ser site on the IRS protein in the phosphorylated insulin signaling pathway and consequently resulting in insulin resistance." (PMID 35811658, 2022). "Supporting the dependence of proinflammatory functions of ATMs on their glycolytic metabolism, HFD-fed mice with PDK2/4-deficient bone marrow display lower ATM numbers and inflammation (TNFα, IL-6 and CCL2 expression) in WAT as well as ameliorated insulin resistance." (PMID 34876704, 2022). "For example, immune cell-derived proinflammatory cytokines such as TNF block insulin signaling by inactivating insulin receptor substrate (IRS), leading to insulin resistance and exacerbating blood glucose levels due to the downregulation of glucose transporters on adipocytes." (PMID 34837070, 2022). "Finally, curcumin reduces the levels of tumor necrosis factor-α (TNF-α) and plasma-free fatty acids (FFA) that correlate with insulin resistance." (PMID 35408920, 2022). "Our results showed that GLP could regulate the TNF signaling pathway through AKT1; thus, it might reduce insulin resistance in patients with NASH." (PMID 35811658, 2022). "TNF-α and IL-6 suppress insulin receptor substrates 1 (IRS-1) and 2 (IRS-2) and glucose transporter-4 (GLUT-4) while upregulating suppressor of cytokine signaling-3, resulting in insulin resistance." (PMID 35887592, 2022).
Insulin resistance (continued). "Like miR-16-5p, miR-17-5p was positively correlated with insulin resistance but not TNF-α or BMI in one study." (PMID 36704034, 2022). "In this regard, several studies have shown that anti-TNF therapy (based on the administration of infliximab, etanercept, or adalimumab) was able to reduce insulin resistance—measured by the HOMA-IR—in nondiabetic patients with RA." (PMID 35629988, 2022). "Further, it increases pro-inflammatory cytokine production, including IL-1, IL-6, and tumor necrosis factor (TNF)-alpha which in turn, may alter insulin receptor signaling thereby increasing insulin resistance." (PMID 36578843, 2022). "The inhibition of TNF-α could upregulate AKT phosphorylation in IR-HepG2 cells and improve lipid-induced insulin resistance." (PMID 36120365, 2022). "↑: miR-16-5p, miR-17-5p, miR-20a-5p in pregnant people with GDM compared with controls at each time point.Positive correlation between these miRNAs and insulin resistance, but not with TNF-α or BMI." (PMID 36704034, 2022). "Kupffer cells play a major role in liver insulin resistance induced by HFD feeding through producing various inflammatory mediators, including TNF-α, IL-6, IL-1β, prostaglandins, and reactive oxygen species, which play vital roles in promoting the development of insulin resistance." (PMID 36230963, 2022). "Thirdly, through oxidative stress hyperglycemia enhances the circulating concentrations of proinflammatory cytokines, such as tumor necrosis factor-α (TNF-α) and interleukin-6 (IL-6), leading to insulin resistance and resulting in malicious exacerbation of hyperglycemia." (PMID 35600601, 2022). "Tumor necrosis factor α (TNF-α) is a potent mediator of inflammation, and serum TNF-α levels are significantly increased in DM, and contribute to increased levels of oxidative stress and insulin resistance." (PMID 35739993, 2022). "Third, we had no available data on CRP, insulin resistance, and inflammatory parameters such as tumor necrosis factor and IL-6, since they were not routinely measured." (PMID 35572991, 2022). "Furthermore, the expression of UCP1 and browning stimulus in sWAT promotes the decrease of tumor necrosis factor-alpha (TNF-α), insulin resistance, and regulates mitochondrial dysfunction." (PMID 35484170, 2022). "A drastically upregulated immune system during anti-TB treatment could substantially increase the levels of TNF- α, IFN-γ, and interleukin-17, which could lead to insulin resistance and DM." (PMID 34813631, 2021). "Moreover, IL-6 and TNF-α, are involved in increased hepatic SREBP-1c expression and insulin resistance, via the increased expression of SOCS in the liver." (PMID 33584134, 2021). "In addition, it has been shown that 10 nm GNPs control hyperglycemia in diabetic rats via regulating blood glucose levels, insulin resistance, pro-inflammatory mediators (CRP, IL-6 and TNF-α), and liver enzymes." (PMID 34572503, 2021). "These macrophages secrete TNF-α, IL-6, IL-1b and MCP1, which induce insulin resistance." (PMID 34683361, 2021). "These include adiponectin, resistin, interleukin-6 (IL-6), tumor necrosis factor-α (TNF-α), and monocytic chemotactic protein (MCP-1) that influence not only body weight homeostasis but also insulin resistance, diabetes, lipid levels, inflammation, and atherosclerosis development." (PMID 33865458, 2021). "Moreover, the COVID-19-induced inflammation and cytokine storm (CS), which are characterized by profound elevations in the levels of tumor necrosis factor-alpha (TNF-α) and interleukin (IL)-6, lead to peripheral insulin resistance (IR)." (PMID 34124187, 2021). "TNFα and IL-6, through classical receptor-mediated processes, stimulate both the JNK and the IκB kinase-β (IKK-β)/(NF-κB) pathways, leading to upregulation of inflammation mediators, and further to insulin resistance." (PMID 34068151, 2021).